HK2 (hexokinase 2)
Diseases named in the same sentence as HK2 in open-access papers (continued):
Sharing a sentence is not in itself a finding about the gene and the disease.
cervical carcinoma (continued). "Targeting HK2 was found to reduce the glycolysis of cervical cancer cells and enhance the sensitivity of cervical cancer to RT." (PMID 36313645, 2022). "Knockdown of HK2 in cervical cancer cells inhibited proliferation and migration and promoted cell apoptosis." (PMID 36313645, 2022). "Inhibiting HK2 to reduce the dependence of cervical cancer cells on glycolysis is a potential strategy to promote cervical cancer RT." (PMID 36313645, 2022). "We then confirmed the expression changes of some of the identified marker genes (OSMR, SNAI1, and HK2) for the cluster in HeLaS3 and SiHa cervical cancer cell lines by RT-qPCR." (PMID 36551576, 2022). "Previously, knockdown of HK2 in cervical cancer cells has been observed to inhibit expression of AKT and mTOR, which are involved in cancer progression." (PMID 35184747, 2022). "In HPV-positive cervical cancer cells, the enzyme hexokinase 2 (HK2) is increased compared to HPV-negative tumour cells due to the Warburg effect; and its inhibition leads to re-sensitisation to radiation therapy." (PMID 33807087, 2021). "We further identified that circCDKN2B-AS1 facilitates aerobic glycolysis by interacting with the IMP3 protein to stabilize HK2 mRNA, consequently promoting the malignant phenotype in cervical cancer cells." (PMID 33308298, 2020). "Utilization of an inhibitory peptide to block the interaction between circCDKN2B-AS1 and the IMP3 protein impeded the binding of IMP3 to the 3’UTR of HK2 mRNA and suppressed aerobic glycolysis in cervical cancer cells." (PMID 33308298, 2020). "A transcriptome sequencing analysis was performed in HK2-overexpressing monoclonal cell lines to screen for potential target genes and signal transduction pathways that are likely involved in HK2-mediated cell growth and tumor formation in cervical cancer." (PMID 33324557, 2020). "Recently, immunohistochemistry analysis also showed that approximately 60% of cervical cancer specimens (n=197) stained positive for HK2." (PMID 33324557, 2020). "In cervical cancer, increased HK2 expression in cervical cancer samples compared to normal cervical tissues was already reported as early as the 1970s." (PMID 33324557, 2020). "The relative expression levels of HK2 in these cervical carcinoma samples were higher than that in the normal cervical samples (p<0.05)." (PMID 33324557, 2020). "A total of 105 HK2-modified cells and their control cells were inoculated subcutaneously into female nude mice for tumor formation assay to identify the effect of HK2 in cervical cancer cells in vivo." (PMID 33324557, 2020). "For instance, the lncRNA-UCA1 has been shown to modulate radioresistance in cervical cancer cell through the HK2/glycolytic pathway." (PMID 33123468, 2020). "The expression level of circCDKN2B-AS1 fated the binding of IMP3 to the 3′ untranslated region (UTR) of HK2 mRNA, consequently affecting the malignant cell phenotype and aerobic glycolysis in cervical cancer in vitro and in vivo." (PMID 33308298, 2020). "To analyse the functional role of HK in tumor progression, we established several stable HK1 or HK2 knockdown lines in human cervical carcinoma HeLa cells using the RNAi-mediated gene silencing approach." (PMID 29721175, 2018). "Thus, in our work, the anti-Warburg mechanism of Ginsenoside F2 was elucidated in cervical cancer cells in relation to miR193a-5p and the c-Myc/β-catenin/HK2 signaling axis." (PMID 39273365, 2024). "Hexokinase 2 (HK2), the initial rate-limiting enzyme in glucose metabolism, catalyzes the conversion of glucose to glucose-6-phosphate (G-6-P) and exhibits significantly increased expression in cervical cancer tissues." (PMID 38577616, 2024). "The m6A methyltransferase METTL3 links to the 3’-untranslated region of HK2 mRNA and recruits YTHDF1 to ensure HK2 stability, ultimately boosting aerobic glycolysis in cervical cancer (CC) cells, contributing to their proliferation and leading to poor prognosis in cervical cancer." (PMID 37055798, 2023).
cervical carcinoma (continued). "Previous studies have also found that cervical cancer cells can reprogram cellular metabolic pathways so that these cervical cancer cells can benefit from increased expression of hexokinase 2, providing metabolites and intermediates of tricarboxylic acids for their growth." (PMID 37510286, 2023). "Taken together, overexpression of hypoxia-pathway-related genes, such as NDRG1, HK2, and PLOD2, is induced by the OSM-STAT3 axis, and higher expression levels of these genes are significantly associated with poor prognosis in cervical cancer patients." (PMID 36551576, 2022). "In addition, IMP3 was upregulated in HPV16-positive cervical cancer and precancerous tissues compared with normal tissues and facilitated aerobic glycolysis by stabilizing HK2 mRNA, consequently promoting the malignant phenotype in cervical cancer cells." (PMID 35706003, 2022). "Moreover, METTL3 recruited YTHDF1 to enhance HK2 stability, thereby promoting the Warburg effect of cervical cancer." (PMID 34185971, 2022). "Similarly, YTHDF1 is recruited to m6A-modified HK2 and increases its mRNA stability in cervical cancer, thereby promoting HK2 translation." (PMID 36289851, 2022). "Additionally, the protein level of HK2 in eight cervical carcinoma samples and eight normal cervical samples was detected by western blotting." (PMID 33324557, 2020). "Moreover, HK2 expression was observed in all five cervical cancer cell lines using western blotting and immunocytochemistry (HeLa, SiHa, C-33 A, CaSki, and HT-3), and a relatively low expression of HK2 was observed in HeLa and SiHa cells." (PMID 33324557, 2020). "All of these results suggested that HK2 expression was stimulated in cervical carcinoma tissues and might be involved in the process of cervical carcinogenesis." (PMID 33324557, 2020). "In cervical cancer, stimulated HK2 expression was already observed back in the 1970s." (PMID 33324557, 2020). "All of these results demonstrated that the HK2 protein could promote the proliferation of cervical carcinoma cells in vitro." (PMID 33324557, 2020). "In this study, both the in vitro and in vivo experiments revealed that HK2 could promote cell proliferation and tumor formation in cervical cancer." (PMID 33324557, 2020). "Importantly, however, HK2 repression upon silencing endogenous E6/E7 expression was only observed in HeLa cells among 8 different tested HPV-positive cervical cancer and HNSCC cell lines." (PMID 29290953, 2017). "Thus, we hypothesized that circCDKN2B-AS1 stabilizes HK2 mRNA and facilitates aerobic glycolysis in cervical cancer by recruiting the IMP3 protein to the 3’UTR of HK2 mRNA." (PMID 33308298, 2020). "Our findings demonstrate that circCDKN2B-AS1 facilitates aerobic glycolysis by sponging the IMP3 protein to stabilize HK2 mRNA, consequently promoting the malignant phenotype in cervical cancer, which may provide a potential approach for cervical cancer therapeutics." (PMID 33308298, 2020). "Our study suggested that AZD8055-mediated cervical cancer cell proliferation inhibition may occur through deregulating mTOR activity and upregulating the expression of miR-143, whose targets include HK2, a key time-limiting enzyme in the process of glucose activation." (PMID 23420667, 2013). "hOGG1 and HK-2 might play a key role at the early stage of cervical cancer, and the findings of hOGG1 and HK-2 should be considered as a significant biomarker at the early stage of cervical cancer." (PMID 20846459, 2010). "Significantly, METTL3 also enhances the stability of HK2 mRNA through YTHDF1 mediated m6A modification, thereby promoting aerobic glycolysis in cervical cancer." (PMID 40097750, 2025). "It is recruited by METTL3 to enhance the stability of hexokinase 2 (HK2), exerting an oncogenic factor by promoting the Warburg effect (aerobic glycolysis) in cervical cancer." (PMID 39342406, 2024).
cervical carcinoma (continued). "In summary, GF2 increased the cytotoxicity and the sub-G1 phase along with the suppression of pro-PARP, pro-cas3, Wnt, β-catenin, c-Myc, HK2, LDHA, and PKM2 in cervical cancer cells." (PMID 39273365, 2024). "METTL3 enhanced the HK2 stability through YTHDF1-mediated m6A modification, thereby promoting the Warburg effect in cervical cancer." (PMID 36058934, 2022). "And HK2 also promoted cell motility and distant metastasis by elevating fibronectin/MMP2/MMP9 in cervical cancer cells." (PMID 35953860, 2022). "METTL3 targets the 3′-UTR of hexokinase 2 (HK2) mRNA to enhance HK2 stability in a YTHDF1-dependent manner, which promotes the proliferation and aerobic glycolysis of cervical cancer cells." (PMID 36008936, 2022). "METTL3-induced m6A modification recruits m6A readers to stabilize hexokinase 2 (HK2) mRNA at the 3’ untranslated region, thus increasing HK2 expression and promoting the Warburg effect in esophageal carcinoma, CRC and cervical cancer." (PMID 36289851, 2022). "The colony formation and transwell assays results showed that reduced AK4, HK2, P4HA1, TGFBI and VEGFA expression, which significantly inhibited proliferation, migration and invasion ability of cervical cancer cells." (PMID 34217310, 2021). "The functional study shown that expression of AK4, HK2, P4HA1, TGFBI and VEGFA can regulate the proliferation, migration, and invasion ability of cervical cancer cells in vitro." (PMID 34217310, 2021). "The results obtained with RT-PCR and immunohistochemistry assays both showed that AK4, HK2, P4HA1, TGFBI and VEGFA were all highly expressed in these cervical cancer tissue samples." (PMID 34217310, 2021). "For example, m6A methyltransferase METTL3 is significantly upregulated in cervical cancer tissue and cells and promotes the proliferation, Warburg effect (aerobic glycolysis) through targeting the 3′-UTR of HK2 mRNA to enhance HK2 stability." (PMID 34392306, 2021). "The functional study shown that expression of AK4, HK2, P4HA1, TGFBI and VEGFA can regulate the proliferation, migration, and invasion ability of cervical cancer cells." (PMID 34217310, 2021). "To explore the unsettled puzzle, develop more significant biomarker of cervical cancer and cervical precancerous lesions, we analyzed the expression of hOGG1, VDAC1 and HK-2 in cervical biopsy tissue." (PMID 20846459, 2010). "METTL3 maintained HK2 stability via YTHDF1-mediated m6A, driving Warburg effect in cervical cancer." (PMID 39060874, 2024). "METTL3 modifies HK2 mRNA with m6A at the 3’UTR of HK2 mRNA, and also recruit YTHDF1 to combine with HK2 mRNA to improve the stability of HK2 mRNA and promote the aerobic glycolysis of cervical cancer." (PMID 37582735, 2023). "In cervical cancer (CC) cells, YTHDF1 accelerates m6A-augmented glycolysis and cancer progression by promoting translational elongation of pyruvate dehydrogenase kinase 4 (PDK4) mRNA and stabilization of hexokinase 2 (HK2) mRNA." (PMID 36999016, 2023). "Overall, our findings suggest that the hypoxia-related genes, including NDRG1, HK2, and PLOD2, can be controlled by inhibiting STAT3, and this strategy is a novel therapeutic option that may effectively reduce the progression of cervical cancer." (PMID 36551576, 2022). "Furthermore, HeLa-IRR and SiHa-IRR cells can increase glycolysis by increasing Hexokinase 2 (HK2), PKM, HIF-1α and GLUT-1 expression levels, and increase radiation resistance of cervical cancer cells." (PMID 35692795, 2022). "In particular, the NDRG1, HK2, PLOD2, EGLN3, and NPC1 genes showed a higher expression in tumors than in normal tissues, and cervical cancer patients overexpressing these genes had a poor prognosis compared with those who showed low expression levels of these genes." (PMID 36551576, 2022).
cervical carcinoma (continued). "The process of aerobic glycolysis in cervical cancer cells is mediated by key enzymes such as glucose transporter 1 (GLUT1), LDHA, hexokinase 2 (HK2) and aldolase A (ALDOA), which enhance glucose uptake and lactate production, and promote the progression of cervical cancer." (PMID 36313645, 2022). "Moreover, the result of RT-PCR and immunohistochemistry demonstrated that AK4, HK2, P4HA1, TGFBI and VEGFA were all highly expressed in these cervical cancer tissue samples." (PMID 34217310, 2021). "Moreover, the results of qPCR and immunohistochemistry staining assay revealed that the expression of AK4, HK2, P4HA1, TGFBI and VEGFA is high in cervical cancer." (PMID 34217310, 2021). "Furthermore, to verify the accuracy of the 5-gene signature, we examined the expression of the signature genes (AK4, HK2, P4HA1, TGFBI and VEGFA) in clinical samples from 10 cervical cancer patients by qPCR and IHC analysis." (PMID 34217310, 2021). "Thus, our results suggest that circCDKN2B-AS1 facilitates aerobic glycolysis and the progression of cervical cancer via interacting with IMP3 and HK2 mRNA in vivo." (PMID 33308298, 2020). "However, the potential links between HK2 and the Raf/MEK/ERK signaling pathway, which mediates cervical carcinoma initiation and growth, remain less known." (PMID 33324557, 2020). "However, further research is necessary to investigate the potential molecular regulation mechanism by which HK2 participated in upregulating ERK1/2 mRNA expression and stimulating p-Raf and p-MEK1/2 expression in cervical cancer cells." (PMID 33324557, 2020). "Liu and collaborators observed that HK2 enzyme is increased in HPV-infected cervical cancer cells, compared to those negative to HPV, and that the inhibition of HK2 activity in HPV-positive cells makes these cells radiosentive." (PMID 29932118, 2018). "In this study, we first showed that HK1 but not HK2 knockdown induced a typical EMT switch in human cervical cancer cells." (PMID 29721175, 2018). "In recent immunohistochemistry analyses, normal cervical tissues exhibited little or no HK2 signals whereas approximately 60% of the cervical cancer specimens (n = 197) stained positive for HK2." (PMID 29290953, 2017). "Studies reporting increased HK2 expression and activity in cervical cancers compared to normal cervical epithelium date back to the 1970s." (PMID 29290953, 2017). "Therefore, it was interesting to explore whether there had a potential HK2-ERK-cyclin A1/p27 signaling cascade on regulating cell proliferation and tumor formation in cervical cancer." (PMID 33324557, 2020). "As shown in this study, HK2 overexpression could activate ERK1/2 through the Raf/MEK/ERK signaling pathway, further promoting cell proliferation and tumor formation by inducing cyclin A1 and reducing p27 expression in cervical cancer cells." (PMID 33324557, 2020). "In conclusion, this study demonstrated that HK2 could activate ERK1/2 through the Raf/MEK signaling pathway, further promoting cell proliferation and tumor formation by inducing cyclin A1, c-myc and reducing p27 in cervical cancer cells." (PMID 33324557, 2020). "However, the evidences that about the molecular regulation mechanism of HK2 on regulating cell proliferation and tumor formation in cervical cancer cells remains not a lot." (PMID 33324557, 2020). "In cervical carcinoma cells, the HK1 but not HK2 knockdown induced a phenotypic change characteristic of epithelial-mesenchymal transition, which accelerated tumor growth and metastasis." (PMID 36335239, 2022). "In cervical carcinoma cells, the HK1 but not HK2 knockdown induced a phenotypic change characteristic of epithelial-mesenchymal transition, which accelerated tumor growth and metastasis both in vitro and in vivo analyses." (PMID 29721175, 2018).
cervical carcinoma (continued). "Collectively, these results indicate that HK2 protein and mRNA expression are reduced upon E6/E7 repression only in HeLa cells and not in any of the other investigated HPV-positive cervical cancer and HNSCC cell lines." (PMID 29290953, 2017). "However, there is still a lack of studies explaining how FTO acts on HK2 and what pathway FTO regulates cervical cancer cell proliferation through HK2-mediated." (PMID 39175477, 2024).
liver cancer (55 papers, 2015 to 2025). An epithelial or non-epithelial malignant neoplasm that arises from the liver. "HK2 serves as one of the HK family members has the highest affinity for glucose and is up-regulated in liver cancer, which is associated with poor prognosis." (PMID 34975319, 2022). "Of these, the one encoded by the HK2 (hexokinase 2) gene was found to be overexpressed in a variety of cancers, i.e., colorectal, lung, digestive, and liver cancers." (PMID 35328104, 2022). "Recent studies have demonstrated that over-expression of HK2 has been observed in human liver cancer and it is associated with poor overall survival in patients." (PMID 29258429, 2017). "Moreover, analysis of HK1 and HK2 expression in the TCGA liver cancer dataset demonstrates that a substantial portion (83%) of HK2+ (HK2 RSEM > 1000) liver cancers are deficient in HK1 expression (HK1 RSEM < 1000)." (PMID 29988332, 2018). "Notably, this study uncovered a previously unknown connection between the USP14 and HK2 proteins, elucidating the underlying mechanism driving the development of liver cancer." (PMID 38383348, 2024). "miR-181a-5p has been shown to reduce the electron transport chain, resulting in an increase in HK2 and glycolytic activity in liver cancer cells." (PMID 40436833, 2025). "Genistein inhibited HIF-1α protein expression and transcriptional activity, by which the contents of GLUT1 and HK2 in liver cancer cells were down-regulated." (PMID 39991762, 2025). "For instance, knockdown of liver‐specific HK2 inhibits the development of diethyl nitrosamine (DEN)–induced liver cancer in mice." (PMID 41476787, 2025). "The study also explored the newly discovered interaction between USP14 and HK2 protein and further investigated how USP14 regulates the occurrence and development of liver cancer through HK2." (PMID 38383348, 2024). "Licorice roots extract induced apoptosis and cycle arrest of liver cancer cells, inhibited HK2, PKM2, and LDHA enzymes, and inhibited glycolysis by up-regulating multiple tumor suppressor genes miRNAs." (PMID 37663261, 2023). "In particular, the glycolytic enzyme HK2 level increases after the deletion of ATG5 in liver cancer, while ATG7 knockdown increases PKM2 phosphorylation." (PMID 37887330, 2023). "Immunohistochemical staining (IHC) of HK2 in a liver cancer tissue microarray (TMA) containing 93 liver cancer samples and 87 matched normal liver tissues or cirrhosis tissues revealed that high HK2 expression was predictive of shorter OS." (PMID 37524692, 2023). "Studies indicated that SPARC participates in the glycolysis process of liver cancer cells by down-regulating the expression of HK2." (PMID 38076208, 2023). "The possible effectiveness of such a strategy was demonstrated in in vitro experiments, where inhibition of HK2 decreased the viability of autophagy-impaired liver cancer cells." (PMID 37887330, 2023). "Our results, therefore, highlight a transcription‐dependent mechanism of HK2 in stemness regulation in liver cancer." (PMID 35603967, 2022). "The correlation between FGFR/HK2 signaling and liver cancer patients' prognosis was tested in TCGA-LIHC (liver hepatocellular carcinoma) dataset." (PMID 36168616, 2022). "Blocking HK2 or ACSL4 effectively inhibits liver cancer growth, and GalNac‐siHK2 administration specifically targets the growth of orthotopic tumor xenografts." (PMID 35603967, 2022). "We then cloned the full‐length CDS of HK2 into the PCDH vector to overexpress the HK2 protein in liver cancer cells." (PMID 35603967, 2022). "Wogonin inhibits gene expression of glycolytic associated factors like HK2 and LDHA in ovarian and liver cancer cells, hence limiting glycolysis and cell proliferation." (PMID 36339566, 2022). "Due to the importance of glycolysis in the progression of liver cancer, the targeting of key rate-limiting enzymes in the glycolysis pathway (eg. hexokinase 2, phosphofructokinase 1 or type M2 and pyruvate kinase) is a novel approach for HCC treatment." (PMID 35127491, 2021).